TRIM37 (tripartite motif containing 37)
Description:
E3 ubiquitin-protein ligase required to prevent centriole reduplication. Probably acts by ubiquitinating positive regulators of centriole reduplication. Mediates monoubiquitination of 'Lys-119' of histone H2A (H2AK119Ub), a specific tag for epigenetic transcriptional repression: associates with some Polycomb group (PcG) multiprotein PRC2-like complex and mediates repression of target genes. Also acts as a positive regulator of peroxisome import by mediating monoubiquitination of PEX5 at 'Lys-472': monoubiquitination promotes PEX5 stabilitation by preventing its polyubiquitination and degradation by the proteasome. Has anti-HIV activity.
Synonyms: KIAA0898; MUL; POB1; TEF3
Tractability: Antibody: UniProt places it where antibodies can reach, with high confidence. PROTAC: UniProt records ubiquitination sites on it; ubiquitination databases record sites on it.
Gene: Protein-coding gene on chromosome 17 (58,982,638 to 59,106,921, reverse strand). Ensembl gene ENSG00000108395.
Subcellular location: Chromosome; Cytoplasm, perinuclear region; Peroxisome membrane
Pathways (Reactome):
Immune System: Antigen processing: Ubiquitination & Proteasome degradation
Gene Ontology:
Molecular function: histone H2AK119 ubiquitin ligase activity; protein binding; protein homodimerization activity; transcription coactivator activity; tumor necrosis factor receptor binding; ubiquitin protein ligase activity; ubiquitin protein ligase binding; ubiquitin-protein transferase activity; chromatin binding; enzyme binding; zinc ion binding
Biological process: aggresome assembly; negative regulation of centriole replication; negative regulation of gene expression, epigenetic; negative regulation of transcription by RNA polymerase II; protein autoubiquitination; protein import into peroxisome matrix; protein monoubiquitination; protein stabilization; positive regulation of DNA-templated transcription; protein ubiquitination
Cellular component: aggresome; chromosome; cytoplasm; cytosol; ESC/E(Z) complex; peroxisomal membrane; peroxisome; perinuclear region of cytoplasm
Genetic constraint (gnomAD): Loss-of-function variants: 73 observed, 112.43 expected, observed/expected ratio (o/e) 0.65, 90% interval 0.54 to 0.79. The upper end of that interval is the gene's LOEUF score, 0.79, which puts it in group 3 of 6, group 1 being the genes least tolerant of losing a copy. Missense variants: 995 observed, 1,158.9 expected, observed/expected ratio (o/e) 0.86, 90% interval 0.81 to 0.9. Synonymous variants: 373 observed, 387.31 expected, observed/expected ratio (o/e) 0.96, 90% interval 0.88 to 1.05.
Gene-disease validity (ClinGen):
ClinGen rates the evidence that TRIM37 causes each of these diseases.
mulibrey nanism (autosomal recessive): Definitive. A prenatal onset growth disorder with multiorgan manifestations.
Homologues: Orthologues: chimpanzee TRIM37 (99% identical), dog TRIM37 (95% identical), pig TRIM37 (94% identical), mouse Trim37 (93% identical), rat Trim37 (92% identical), macaque TRIM37 (92% identical), rabbit TRIM37 (91% identical), guinea pig TRIM37 (88% identical), tropical clawed frog trim37 (74% identical), zebrafish trim37 (66% identical). Paralogues in human: TRIM24 (14% identical), TRIM33 (13% identical), TRIM9 (12% identical), TRIM66 (12% identical), TRIM2 (12% identical), TRIM67 (12% identical), TRIM46 (12% identical), TRIM3 (11% identical), TRIM71 (11% identical), TRIM36 (11% identical), TRIM28 (10% identical), MID1 (9% identical), and 68 more.
Diseases named in the same sentence as TRIM37 in open-access papers:
TRIM37 is named in the same sentence as 72 diseases in open-access papers, as found by Europe PMC text mining. Sharing a sentence is not in itself a finding about the gene and the disease. The quoted sentences say what the papers report.
breast carcinoma (23 papers, 2018 to 2026). "In TRIM37‐amplified tumours, such as breast cancer, PLK4 inhibition causes centrosomal dysfunction and mitotic abnormalities, resulting in cell death." (PMID 41537447, 2026). "TRIM37 is highly expressed in breast cancer tissue and is associated with poor overall patient survival." (PMID 39614126, 2025). "Here, we describe the mechanism by which TRIM37 associates with breast cancer risk and aggressive phenotype in BW." (PMID 39614126, 2025). "The tests proved that breast cancer risk was significantly higher in samples with high TRIM37 expression." (PMID 39614126, 2025). "We next interrogated the functional locus of rs57141087 to understand its association with TRIM37-driven breast cancer risk." (PMID 39614126, 2025). "We, therefore, examined TRIM37 expression in cancer-free breast tissue from women at higher lifetime risk of developing breast cancer." (PMID 39614126, 2025). "In multivariate analyses, TRIM37 correlated significantly with breast cancer risk (P = 0.0005), BMI (P = 0.003), and near significantly with racial identity (P = 0.0568)." (PMID 39614126, 2025). "The univariate analysis confirmed the significant association between TRIM37 and breast cancer risk (P = 0.00217) and obesity (P = 0.0355)." (PMID 39614126, 2025). "TRIM37 is linked to a 17q gain in neuroblastoma and 17q34 amplification in breast cancer, and has also been shown to cause genomic instability by delaying centrosome maturation." (PMID 39086683, 2023). "Further analyses at the biochemical level are required to determine the exact mechanisms underlying RING1A and TRIM37 deposition of H2AK119ub1 in the context of breast cancer." (PMID 30139998, 2018). "Next, using the χ2 test, we asked whether TRIM37 expression is associated with age, menopause status, breast cancer risk, racial identity, parity status, and BMI." (PMID 39614126, 2025). "In TRIM37‐amplified tumours (such as neuroblastoma and breast cancer), PLK4 inhibition induces centrosomal dysfunction and mitotic abnormalities, ultimately leading to cell death—a synthetic lethal effect." (PMID 41537447, 2026). "It was also reported that the treatment of breast cancer cells that overexpressed 17q23/TRIM37 with centrinone hindered the mitotic spindle assembly and accelerated cell death." (PMID 41488365, 2025). "Similar results were obtained in patient-derived organoids presenting PLK4 as a target of therapy in TRIM37-amplified cases of breast cancer." (PMID 41488365, 2025). "It was shown that treatment of breast cancer cells that overexpressed 17q23/TRIM37 with PLK4 inhibitor hindered the mitotic spindle assembly and accelerated cell death." (PMID 41488365, 2025). "The TRIM37 gene is located at the 17q22‐17q23 region, which is amplified in numerous tumor types, particularly in breast cancer and neuroblastoma." (PMID 40257113, 2025). "Gene Set Enrichment Analysis (GSEA) analysis identified CSC and EMT terms highly enriched in 51-G upregulated genes (Figs. EV4L and 4K) in concordance with TRIM37 function in tumorigenesis and breast cancer progression." (PMID 39614126, 2025). "Together, our results indicate that risk variant rs57141087 brings enhancer in contact with TRIM37 promoter in cis through NRF1 binding to induce precise gene expression changes triggering neoplastic transformation and breast cancer progression." (PMID 39614126, 2025). "Other new compounds targeting PLK4 have been shown to specifically lead to anticancer effects in TRIM37-amplified breast cancer models." (PMID 41092110, 2025). "TRIM37 plays an important function in centrosome regulation and is commonly amplified in breast cancer.When PLK4 is inhibited by centrinone, cell division takes place without centrosome duplication, leading to delayed, acentrosomal spindle assembly." (PMID 41092110, 2025). "Our previous studies comprehensively described tripartite motif-containing protein 37 (TRIM37) function as a novel breast cancer oncoprotein." (PMID 39614126, 2025).
breast carcinoma (continued). "RP-1664 disrupts centriole biogenesis in cancer cells and shows excellent efficacy in pre-clinical TRIM37-amplified models, including breast cancer." (PMID 41092110, 2025). "It was previously shown that the 17q23 chromosomal amplification, harbouring TRIM37, promotes sensitivity to centrinone in breast cancer cells." (PMID 38324534, 2024). "We have shown that LSD1 suppresses breast cancer metastasis by inhibiting the expression of tripartite motif containing 37 (TRIM37) and inducing the transcription of GATA binding protein 3 (GATA3)." (PMID 38448424, 2024). "TRIM37 is part of the 17q23 amplicon present in approximately 18% of breast cancer tumors and overexpression of TRIM37 in these lines renders them sensitive to the PLK4 inhibitor centrinone." (PMID 35758262, 2022). "In clinical analyses, we find TRIM37 is upregulated in multiple breast cancer datasets, supporting our findings that the TRIM37-AP-2γ interaction is essential for breast cancer tumor growth." (PMID 35864973, 2022). "Herein, using a proteomics approach, we identified Tripartite motif-containing 37 (TRIM37) as a novel coactivator of AP-2γ-mediated transcription in breast cancer cells." (PMID 35864973, 2022). "Overall, our work reveals that TRIM37 is an oncogenic coactivator of AP-2γ in breast cancer and provides a novel therapeutic target for treating the disease." (PMID 35864973, 2022). "Previous studies showed that TRIM37 exerted histone H2A ubiquitination and drive centrosome dysfunction of breast cancer." (PMID 34130705, 2021). "For example, TRIM37 is overexpressed in breast cancers and promotes tumor progression by acting as an oncogenic H2A ubiquitin ligase and suppressing the activity of several tumor suppressor proteins." (PMID 33194618, 2020). "A PLK4 inhibitor, CFI-400945, triggers mitotic catastrophe in breast cancer cells overexpressing TRIM37." (PMID 33054808, 2020). "TRIM37 has also been shown to promote the proliferation, invasion and migration in breast cancer, lung cancer, gastric cancer, glioma, and pancreatic cancer." (PMID 33414811, 2020). "The Chr17q region containing the TRIM37 gene is frequently amplified in neuroblastoma, as well as breast cancer." (PMID 33054808, 2020). "The genomic region hosting the TRIM37 gene (17q23) is amplified in more than one third of breast cancers, and TRIM37 expression is increased in breast tumor." (PMID 30586926, 2018). "The UBCH5 isoforms ubiquitinate histone H2A in concert with PRC1 in vitro, and TRIM37, an E3 ligase that associates with PRC2, ubiquitinates H2A in human breast cancer cell lines where RING1B of PRC1 is down-regulated." (PMID 30282802, 2018). "TRIM37 was recently proposed as a novel histone H2A ubiquitin ligase in breast cancer cells, with a chromosomal copy-number amplification at 17q2343." (PMID 30139998, 2018). "A synthetic lethal relationship between PLK4 inhibition and TRIM37 overexpression in cancers with amplifications or gains of the chromosomal region 17q23, commonly observed in breast cancer and neuroblastoma, has brought PLK4 inhibitors into the spotlight as potential therapeutics." (PMID 40257113, 2025). "Finally, context-dependent TRIM37 expression reveals that early-stage TRIM37 levels affect the initiation and trajectory of breast cancer progression." (PMID 39614126, 2025).
breast carcinoma (continued). "TRIM37 mono-ubiquitinates histone H2A in the MCF-7 breast cancer cell line, and this has been reported to dampen the expression of thousands of genes, including tumors suppressors, thus offering a potential link between TRIM37 overexpression and tumorigenesis." (PMID 33491649, 2021). "As a novel cancerous gene, TRIM37 could mono-ubiquitinate histone H2A to promote breast cancers tumorigenesis, and also regulate chemotherapeutic sensitivity via DNA repair way." (PMID 34130705, 2021). "The chromosomal region 17q23 where TRIM37 resides is amplified in ~40% of breast cancers." (PMID 33491649, 2021). "The amplification of the TRIM37 genome contributes to the tumor progression in colorectal cancer, HCC, lung cancer, neuroblastoma, breast cancer, pancreatic cancer, and osteosarcoma." (PMID 36900050, 2023). "Tripartite motif-containing 37 (TRIM37), a member of the TRIM family, is an oncogenic H2A ubiquitin ligase that is overexpressed in a subset of breast cancers and promotes transformation by facilitating the silencing of tumor suppressors." (PMID 37587140, 2023).
mulibrey nanism (12 papers, 2009 to 2026). "Mulibrey nanism is a rare autosomal recessive multisystem disorder caused by biallelic loss of function variants in TRIM37 encoding a peroxisomal E3 ubiquitin ligase." (PMID 42123650, 2026). "Whole exome sequencing (WES) of DNA samples from the proband/mother duo revealed two novel heterozygous missense variants [c.199C>T (p.Arg67Cys)] and [c.2041C>G (p.Gln681Glu)] in the TRIM37 gene, which has been associated with Mulibrey nanism." (PMID 41907767, 2026). "Dysregulation of the E3 ubiquitin ligase TRIM37 is associated with tumor formation and Mulibrey nanism, a recessive developmental syndrome." (PMID 41446055, 2025). "Loss-of-function mutations in the TRIM37 gene cause an autosomal recessive disorder termed Mulibrey nanism." (PMID 35445021, 2022). "TRIM37 is an E3 ubiquitin ligase mutated in Mulibrey nanism, a disease with impaired organ growth and increased tumor formation." (PMID 33491649, 2021). "Individuals with loss-of-function mutations in both copies of TRIM37 are born with a rare disorder known as Mulibrey nanism (Muscle-liver-brain-eye nanism)." (PMID 33491649, 2021). "Mutations in TRIM37 are associated with Mulibrey Nanism in humans, an extremely rare autosomal recessive disorder characterized by profound growth delays and abnormalities of the muscles, liver, brain, and eyes." (PMID 30717660, 2019). "Mulibrey nanism is a rare autosomal recessive syndrome caused by a mutation in the TRIM37 gene with severe growth retardation and multiple organ involvement." (PMID 28496510, 2016). "Conversely, loss-of-function mutations in TRIM37 are the only known cause of Mulibrey nanism (MUL), an autosomal recessive growth disorder." (PMID 41446055, 2025). "Mulibrey nanism (MUL) is a monogenic growth disorder caused by mutations in TRIM37, with pre‐and postnatal growth failure, typical craniofacial features, perimyocardial heart disease, infertility and predisposition to tumors." (PMID 39558672, 2025). "Mulibrey nanism (MUL) is a rare disorder caused by TRIM37 gene variants characterized by growth failure, dysmorphic features, congestive heart failure (CHF), and an increased risk of Wilms’ tumor." (PMID 38116000, 2023). "Mulibrey nanism (MUscle-LIver-BRain-EYe nanism, MUL, OMIM #253250) is a rare autosomal recessive disorder caused by biallelic loss of function variants in the TRIM37 gene (tripartite motif–containing protein 37, OMIM # 605073)." (PMID 38116000, 2023). "Fibroblasts from patients with Mulibrey nanism have Centrobin-containing condensates as do the cultured cell lines depleted of TRIM37." (PMID 35445021, 2022). "Here, we set out to further explore the nature of such supernumerary foci to uncover the mechanism of action of TRIM37, and thereby perhaps also provide novel insights into Mulibrey nanism." (PMID 33491649, 2021). "Genes mediating mitochondrial and peroxisomal fission, and pexophagy show no tissue specificity, except for the neuronal fission factor GDAP1, and cerebral enrichment of the E3 ubiquitin ligase TRIM37, which corresponds to the primary neurological phenotype in mulibrey nanism." (PMID 38365851, 2024).
glioma (7 papers, 2020 to 2024). A benign or malignant brain and spinal cord tumor that arises from glial cells (astrocytes, oligodendrocytes, ependymal cells). "TRIM37 has been implicated in playing a role in the tumorigenesis of breast cancer, human glioma, non-small lung cancer, and gastric cancer." (PMID 35163097, 2022). "TRIM37 is upregulated in glioma samples, and suppression of TRIM37 inhibited glioma proliferation and migration, and induced apoptosis." (PMID 39335533, 2024). "TRIM37 was found to be significantly overexpressed, both at the mRNA and protein level, in glioma tissues and cell lines in contrast with adjacent normal tissues and human astrocytes." (PMID 36139694, 2022). "Recent studies demonstrated that TRIM37 markedly promoted metastasis of glioma cells and lung cancer cells through activating PI3K/Akt signaling pathway, implying a positive regulatory network between TRIM37 and PI3K/AKT in tumor." (PMID 36923153, 2022). "Another study indicated that TRIM37 can promote the migration and invasion of glioma cells by activating the PI3K/Akt signaling pathway and enhance colon cancer metastasis by inducing EMT process." (PMID 36249749, 2022). "For instance, an oncogenic role for TRIM37 in glioma progression has been reported since TRIM37 targets proliferation, migration/invasion, and the epithelial–mesenchymal transition (EMT) via the regulation of the PI3K/Akt pathway." (PMID 36139694, 2022). "In glioma, for example, TRIM37 has been found to have aberrantly high expression." (PMID 38115822, 2023). "If it can be understood why TRIM37 overexpression in glioma and truncation in MULIBREY can similarly lead to tumorigenesis, opportunities to treat both might be identified." (PMID 38115822, 2023). "TRIM37 has been reported to promote the migration and invasion of glioma cells in vitro; therefore, we investigated whether TRIM37 could enhance the migration and invasion of pancreatic cancer cells." (PMID 35163097, 2022). "Moreover, knockdown of TRIM37 impeded proliferation, migration, and invasiveness of glioma cells." (PMID 36139694, 2022).
hepatocellular carcinoma (7 papers, 2020 to 2025). A malignant tumor that arises from hepatocytes. "ROS can upregulate TRIM37 during HBV (Hepatitis B)-associated hepatic fibrosis which is a high risk factor for hepatocellular carcinoma." (PMID 36261847, 2022). "For instance, TRIM52, TRIM37, and TRIM47 have been linked to ovarian cancer invasion, while other members, such as TRIM37 in hepatocellular carcinoma and TRIM24 in colorectal cancer, are known to facilitate metastasis in other cancer types." (PMID 39937005, 2025). "It has been demonstrated that TRIM37 facilitates the invasion and metastatic ability of cells in gastric cancer and hepatocellular carcinoma via activation of the epithelial-mesenchymal transition (EMT) and Wnt/β-catenin signaling pathway, respectively." (PMID 35163097, 2022). "In hepatocellular carcinoma, TRIM37 activated the Wnt/β-catenin pathway from promoting metastasis, and the overexpression of TRIM37 increased the number of lung metastatic nodules in vivo." (PMID 35163097, 2022). "We previously showed that TRIM37 is an oncogene that promotes PC and hepatocellular carcinoma via β-catenin and PI3K–AKT signaling." (PMID 33194618, 2020). "We previously showed that TRIM37 promotes the migration of PC and hepatocellular carcinoma cells." (PMID 33194618, 2020). "For example, lncRNA RP11-286H15.1 binds to PABP cytoplasmic 4 (PABPC4) and promotes its ubiquitination, thus reducing the stability of tripartite motif-containing protein 37 (TRIM37) and cell division cycle protein 27 (CDC27) mRNAs in hepatocellular carcinoma (HCC) cells." (PMID 37225681, 2023).